MIF (macrophage migration inhibitory factor)
Diseases named in the same sentence as MIF in open-access papers (continued):
Sharing a sentence is not in itself a finding about the gene and the disease.
chronic obstructive pulmonary disease (6 papers, 2018 to 2025). A chronic and progressive lung disorder characterized by the loss of elasticity of the bronchial tree and the air sacs, destruction of the air sacs wall, thickening of the bronchial wall, and mucous accumulation in the bronchial tree. "Macrophage migration inhibitory factor (MIF) is a cytokine found to be associated with chronic obstructive pulmonary disease (COPD)." (PMID 33046825, 2020). "Other studies highlighted MIF role as a biomarker for the assessment of PAH associated with chronic obstructive lung diseases." (PMID 30083544, 2018). "A prior study established a biomarker risk score utilizing circulating MIF levels and five additional proteins to prognosticate sarcopenia in patients with chronic heart failure and chronic obstructive pulmonary disease that highlights the potential role of MIF in certain myopathies." (PMID 39517120, 2025). "In this study, we investigated the effects of estrogen and GPER on HIF-1a and MIF expression, cardiac arrhythmias, and inflammation during hypobaric hypoxia." (PMID 40108505, 2025). "Interestingly, high-risk patients exhibited pronounced MIF-mediated reciprocal actions among macrophages/epithelial cells and CD8 positive T, suggesting a potential mechanism of T cell dysfunction in immune-cold tumors." (PMID 41488652, 2025).
cognitive decline (6 papers, 2017 to 2025). "MIF is associated with biomarkers of AD pathology and predicts cognitive decline in MCI and mild dementia." (PMID 36824264, 2023). "MIF levels are significantly elevated in the cerebrospinal fluid in MCI and AD, and higher MIF levels are associated with accelerated cognitive decline in MCI and mild dementia." (PMID 36824264, 2023). "To explore a possible molecular mechanism by which CD74high microglia may contribute to cognitive decline, we investigated the association between MIF protein expression and both clinical and pathological AD diagnoses." (PMID 41282231, 2025). "MIF protein expression was also associated with the slope of cognitive decline (p = 0.0015)." (PMID 41282231, 2025).
dermatitis (6 papers, 2018 to 2024). An inflammatory process affecting the skin. "Similarly, MIF deficiency also significantly reduced disease in the IL-23-induced dermatitis model, suggesting that MIF is involved in the pathogenic pathways activated by IL-23 and required to achieve full-blown psoriasiform dermatitis." (PMID 30333830, 2018). "However, it is currently unclear whether the inverse correlation between MIF and inflammation is merely an epiphenomenon associated with wound-healing processes following acute inflammatory phases or if MIF indeed plays a regulatory role in skin inflammation." (PMID 37507892, 2023). "Astaxanthin administration was found to improve the dermatitis and pruritus via the suppression of mRNA and protein expressions of eotaxin, macrophage migration inhibitory factor (MIF), IL-4, and IL-5." (PMID 33207669, 2020). "This contribution of radioresistant cell-derived MIF for skin inflammation was also reflected on the histopathological level, where epidermal hyperplasia was reduced in Mif−/− → wild-type and Mif−/− → Mif−/− chimera." (PMID 30333830, 2018). "To elucidate the role of MIF in murine psoriasiform dermatitis, we first compared skin inflammation in wild-type and Mif−/− mice in the IIPD mouse model." (PMID 30333830, 2018). "To this end, we scrutinized the role of MIF in the IL-23-induced dermatitis mouse model." (PMID 30333830, 2018). "In a model of chemical skin injury and dermatitis, CD74 on invariant natural killer T (iNKT) cells interacted with MIF to promote iNKT cell migration to the skin." (PMID 33804792, 2021). "In this study, we show that MIF is highly expressed in psoriasiform skin lesions in both the IIPD and the IL-23-induced dermatitis model." (PMID 30333830, 2018).
endometrial cancer (6 papers, 2015 to 2024). Primary or metastatic malignant neoplasm involving the endometrium (mucous membrane that lines the endometrial cavity). "Previous studies have shown that the expression of integrin β3 in endometrial cancer cells can be regulated by progesterone, macrophage migration inhibitory factor, and gonadotropin-releasing hormone." (PMID 26384307, 2015). "Further research is needed to clarify the role of MIF in endometrial carcinoma progression." (PMID 38732068, 2024). "Unlike other cancers, MIF tumor enrichment in endometrial carcinomas is correlated with lower metastatic potential given lower histological grade and lympho-vascular invasion compared to healthy tissue." (PMID 38732068, 2024).
endothelial dysfunction (6 papers, 2015 to 2024). In vascular diseases, endothelial dysfunction is a systemic pathological state of the endothelium (the inner lining of blood vessels) and can be broadly defined as an imbalance between vasodilating and vasoconstricting substances produced by (or acting on) the endothelium. "The link between endothelial dysfunction and MIF in animals models with chronic PAH has been established." (PMID 30083544, 2018). "Taken together, MIF is a novel shear stress-sensitive cytokine, the expression of which is high in atherosclerotic-prone areas and is low in athero-resistant segments in vivo, suggesting a potential role of MIF in OS-induced endothelial dysfunction." (PMID 29403061, 2018). "Given that MIF may play a role in the induction of autophagy and autophagy may relate to dysfunction of the endothelial barrier, we rationalized that MIF may induce endothelial dysfunction through autophagy, resulting in vascular leakage." (PMID 25617421, 2015).
Glucose intolerance (6 papers, 2013 to 2025). Glucose intolerance (GI) can be defined as dysglycemia that comprises both prediabetes and diabetes. "In this study, MIF gene interference improves glucose intolerance, which is likely attributed to the improvement of pancreas function or insulin related receptor." (PMID 25661015, 2015). "We also evaluated predicted signaling from myofibroblast and preadipocytes to IMs, which showed increased MHC-II, CD99, MIF, periostin, amyloid beta precursor protein (APP), and CSF signaling pathways with glucose intolerance and have been implicated in macrophage polarization." (PMID 37711619, 2023). "On the basis of it, we further performed a study on whether MIF has an effect on improvement of glucose intolerance of DM apoE−/− mice by GTT." (PMID 25661015, 2015). "While MIF gene interference could effectively improve glucose intolerance." (PMID 25661015, 2015).
Graves disease (6 papers, 2014 to 2022). Graves' disease is an autoimmune disorder that leads to overactivity of the thyroid gland (hyperthyroidism).It is caused by an abnormal immune system response that causes the thyroid gland to produce too much thyroid hormones. "In a case-control study, the influence of Macrophage Migration Inhibitory Factor (MIF) gene polymorphism on the clinical severity of Graves’ disease was investigated." (PMID 36556267, 2022). "Distributions of alleles and genotypes of the MIF polymorphisms among patients with Graves disease and healthy controls." (PMID 24667663, 2014). "Distributions of alleles and genotypes of the MIF polymorphisms with respect to the severity of goiter in patients with untreated Graves disease." (PMID 24667663, 2014). "Odds ratios of severity of goiter cases categorized by MIF polymorphism rs755622 in patients with untreated Graves disease." (PMID 24667663, 2014). "On the other hand, in patients with Graves disease, treated with radioactive iodine, the inhibition rate of the migration of leukocytes (indicates the production of MIF) appeared to be lower." (PMID 24667663, 2014). "The present study aims to investigate whether single-nucleotide polymorphisms (SNPs) in the MIF and CD74 are risk factors for developing Graves ophthalmopathy (GO) in patients with Graves disease (GD)." (PMID 32744317, 2020). "Clinical significance of MIF genotype in patients with untreated Graves disease." (PMID 24667663, 2014).
Hepatic steatosis (6 papers, 2013 to 2026). Steatosis is a term used to denote lipid accumulation within hepatocytes. "The roles of MIF and MIF-2 in hepatic steatosis and liver lipid metabolism appear to be oppositional." (PMID 40055309, 2025). "High-fat feeding for extended periods elicited evident hyperlipemia, liver steatosis, and cell apoptosis in mice, with inhibited MIF and activated downstream MAPK kinase 4 phosphorylation and JNK." (PMID 36147562, 2022). "Previous evidence has shown that exercise increases the expression of MIF and mediates neuroprotection in rodent models; our results, in agreement with Moon’s research, indicate that MIF is regulated by exercise to prevent hepatic steatosis." (PMID 36147562, 2022). "Several studies provide indication that MIF may also play a role in the development of hepatic steatosis, inflammation and fibrosis." (PMID 26124760, 2015). "The contribution of MIF to HFD-induced hepatic steatosis has been relatively unexplored." (PMID 25412423, 2014). "Taken together, these results indicate that MIF is highly expressed in the liver during physical exercise and may prevent hepatic steatosis by activating the AMPK pathway." (PMID 23823021, 2013). "Together, these results demonstrate that MIF may mediate the preventive effect of exercise against hepatic steatosis through AMPK." (PMID 23823021, 2013). "Although MIF-induced FA oxidation is important for alleviating hepatic steatosis, MIF-induced inhibition of lipogenesis in the liver may be another reasonable mechanism for TG regulation." (PMID 23823021, 2013). "The purpose of this study was to determine the expression level of MIF after exercise in multiple metabolic tissues and to investigate whether MIF protects against hepatic steatosis." (PMID 23823021, 2013). "Based on the relationship between exercise and hepatic steatosis, we hypothesized that MIF may have a crucial role in the prevention of fatty liver disease during exercise." (PMID 23823021, 2013). "We demonstrate that obese MIF−/− mice have reduced hepatomegaly, lower systemic ALT levels and are partially protected from HFD-induced hepatic steatosis; coincident with reduced Pparγ and Srebp-1c mRNA expression compared to WT." (PMID 25412423, 2014). "Hepatic gene expression analyses revealed that lipogenic gene expression (i.e., Cd36, Dgat-1, Fasn, Srebp1-c, Pgc-a1, Lpl, Ppary) was significantly lower in absence of MIF, providing a possible rationale for the observed reduction in hepatic steatosis." (PMID 26124760, 2015).
meningitis (6 papers, 2009 to 2025). A disorder characterized by acute inflammation of the meninges of the brain and/or spinal cord. "Among patients with purulent meningitis, CSF MIF levels were to some degree associated with severity of the infection." (PMID 19558639, 2009). "MIF was significantly increased in the CSF of patients with purulent meningitis and encephalitis, and was to some degree associated with severity of the infection." (PMID 19558639, 2009). "• CSF MIF levels were associated with disease severity in patients with purulent meningitis." (PMID 19558639, 2009). "In the CNS infections however, the trend is the opposite, as a high concentration of MIF in serum and CSF correlates with a more pronounced CNS infection and severe clinical presentation in patients with purulent meningitis." (PMID 28646884, 2017). "The aim of the present study was to investigate CSF MIF levels in 171 patients clinically suspected of having meningitis on admission and to study the use of CSF MIF in the differential diagnosis of meningitis and as a prognostic factor." (PMID 19558639, 2009). "• Patients with purulent meningitis of known aetiology or with encephalitis had significantly higher CSF MIF levels than did patients with lymphocytic meningitis or patients with no CNS infection." (PMID 19558639, 2009). "We investigated cerebrospinal fluid (CSF) levels of MIF in 171 patients who were clinically suspected of having meningitis on admission." (PMID 19558639, 2009). "MIF levels were significantly increased in CSF of patients with purulent meningitis of known aetiology or with encephalitis, and they were to some degree associated with severity of the infection." (PMID 19558639, 2009). "However, further studies should be performed to clarify the release of MIF in CSF and blood during meningitis." (PMID 19558639, 2009). "CSF MIF levels correlated significantly with meningeal inflammation (P < 0.05) but not with systemic inflammatory response (P > 0.05) in patients with purulent meningitis of known aetiology, those with lymphocytic meningitis and those with encephalitis." (PMID 19558639, 2009). "Therefore, to explore further the role played by MIF in bacterial meningitis, experimental meningitis studies with MIF intervention are still warranted." (PMID 19558639, 2009). "Adjunctive therapy with corticosteroids might have a beneficial effect in patients with purulent meningitis who have high CSF MIF levels." (PMID 19558639, 2009). "In patients with purulent meningitis of known aetiology, in patients with lymphocytic meningitis and in patients with encephalitis, CSF MIF levels correlated significantly with meningeal inflammation (P < 0.05) but not with the systemic inflammatory response (P > 0.05)." (PMID 19558639, 2009). "Moreover, CSF MIF levels were to some degree related to disease severity, being significantly higher levels in patients with purulent meningitis who were unconscious or who required assisted ventilation, but CSF MIF levels were not correlated with mortality or presence of septic shock." (PMID 19558639, 2009). "The similarly increased serum MIF concentration in patients with non-TBE meningitis did not correlate with AQ." (PMID 28646884, 2017). "In particular, CSF MIF levels were not useful in differentiating between purulent meningitis of unknown aetiology and lymphocytic meningitis." (PMID 19558639, 2009). "Also, patients with encephalitis (6,937 [3,961 to 8,353]) had significantly higher CSF MIF levels than did those with lymphocytic meningitis (P = 0.004) and patients without meningitis (P < 0.001)." (PMID 19558639, 2009). "In the present study we found that CSF MIF levels were significantly higher in patients with purulent meningitis and encephalitis than in patients with lymphocytic meningitis and patients suspected of having meningitis but without evidence of CNS infection." (PMID 19558639, 2009).
meningitis (continued). "Interestingly, encephalitis patients had high CSF MIF levels despite a minor CSF cellular infiltrate, as compared with meningitis patients, which could indicate that MIF was derived from resident brain cells rather than from CSF inflammatory cells." (PMID 19558639, 2009). "Concentrations of MIF, TNFα, and IL-1β were measured with commercial ELISA in serum and cerebrospinal fluid (CSF) from 36 hospitalized TBE patients, 7 patients with non-TBE meningitis, and 6 controls." (PMID 28646884, 2017). "MIF concentration in serum tended to correlate with AQ in TBE, but not in non-TBE meningitis." (PMID 28646884, 2017).
pancreatitis (6 papers, 2021 to 2026). Inflammation of the pancreas. "The inhibition or loss of MIF resulted in lower TLR4 expression in the lungs of mice following the induction of pancreatitis as well as increased survival outcomes further implicating TLR4 in respiratory distress following the onset of pancreatitis." (PMID 38585277, 2024). "In this study, we aimed to explore the effect of deoxyribonucleic acid (DNA) vaccination producing an auto-MIF antibody on experimental pancreatitis and to provide additional evidence that MIF affects the development of pancreatitis." (PMID 41769625, 2026). "The serum levels of MIF were lower in MIF-DNA vaccinated mice than those in mock-treated mice with pancreatitis." (PMID 41769625, 2026). "In cerulein-induced pancreatitis, the histological findings in the pancreas were ameliorated in MIF-DNA vaccinated mice." (PMID 41769625, 2026). "As for AP, elevations of serum and ascitic MIF levels have been demonstrated in rats with experimental pancreatitis and prophylactic administration of anti-MIF antibody significantly improved the survival rate of the rats." (PMID 33482739, 2021). "Elevations of MIF levels in serum and ascites have been demonstrated in experimental pancreatitis and prophylactic administration of anti-MIF antibody significantly improved the survival rate of the rats." (PMID 33482739, 2021). "MIF-DNA vaccination may be an additional option for the treatment of pancreatitis." (PMID 41769625, 2026). "Another outcome of TLR4 signaling is the production of macrophage migration inhibitory factor (MIF), which has been shown to be a significant indicator of the severity of pancreatitis in both humans and mice." (PMID 38585277, 2024).
renal cell carcinoma (6 papers, 2014 to 2025). "According to an investigation, it was found that miRNA-451 decreased and suppressed renal cell carcinoma proliferation, migration and invasion by inhibiting MIF expression via direct binding, highlighting MIF’s potential as a therapeutic vulnerability." (PMID 41159021, 2025). "According to a study, it was found that MIF knockdown led to decreased proliferation and colon forming ability of renal cell carcinoma." (PMID 41159021, 2025). "MIF’s potential as a biomarker in renal cell cancer remains largely unexplored and so needs more investigation." (PMID 41159021, 2025). "Previous reports of tumor-derived MIF enhanced the progression of renal cell carcinoma and intestinal tumorigenesis." (PMID 26087187, 2015). "Lastly, during the preparation of this manuscript, a study by Pasupuleti and colleagues was published identifying a similar additive and compensatory requirement for MIF and D-DT in controlling cell growth and survival properties of human renal cell carcinoma cell lines." (PMID 24932684, 2014). "High MIF and DDT expression in the kidney impacts renal cell carcinoma (RCC) progression through interactions with HIF1α and HIF2α." (PMID 38732068, 2024).
renal dysfunction (6 papers, 2012 to 2023). "On the other hand, in the examination of renal dysfunction, we found that high MIF and resistin levels were correlated with an increase in serum creatinine in the entire SLE group." (PMID 33133605, 2020). "The AUC for the urinary MIF level in detecting the presence of AKI reached 0.923 in patients with renal dysfunction." (PMID 23319831, 2012). "The median urine MIF levels seemed higher in patients with healthy kidney functions than in those who had renal dysfunction on days 0, 2, and 4, which difference was the biggest on day 0 with medians (and IQRs) of 1268 (725–2626) pg/ml and 638 (461–1467) pg/ml, respectively." (PMID 36631486, 2023). "Therefore, we decided to assess the value of serum MIF, leptin, adiponectin and resistin levels as markers of proteinuria and renal dysfunction in LN." (PMID 33133605, 2020). "However, these may explain the correlations between urinary MIF and the magnitude of proteinuria and degree of renal dysfunction: All those assessments were obtained before the treatment was instituted." (PMID 26272322, 2015). "In subgroup analysis of patients with renal dysfunction on arrival, we revealed that the patients with AKI had an increase in urinary MIF compared to patients with pre-existing CKD." (PMID 23319831, 2012). "Between day 0 and 4 from ICU admission, the urine MIF level changed on average from 2694 ± 686 to 2534 ± 893 pg/ml in patients without renal dysfunction, while from 1774 ± 653 to 2658 ± 918 pg/ml in patients with renal dysfunction." (PMID 36631486, 2023). "The correlation between the urinary MIF level and significant renal dysfunction has not yet been defined." (PMID 23319831, 2012).